NAF1 (nuclear assembly factor 1 ribonucleoprotein)
Diseases named in the same sentence as NAF1 in open-access papers (continued):
Sharing a sentence is not in itself a finding about the gene and the disease.
breast carcinoma (7 papers, 2016 to 2023). "In contrast, apoptosis is activated in NAF-1-deficient human epithelial breast cancer cells." (PMID 29765509, 2018). "In this respect, insulinoma cells are different from epithelial breast cancer cells in which glycolysis was activated upon NAF-1 protein suppression." (PMID 34439408, 2021). "Previously we showed that breast cancer cell lines with suppressed NAF-1/CISD2 expression (grown in culture or xenograft tumors) display features of activated apoptosis." (PMID 29666474, 2019). "Suppressing NAF-1 and MitoNEET reduced breast cancer tumor growth by up to 90% by increasing mitochondrial iron, cellular ROS, and enhancing autophagy." (PMID 31366108, 2019). "NAF-1 and MitoNEET overexpression in breast cancer, hepatocellular carcinoma, pancreatic cancer, cervical cancer are linked to tumor progression." (PMID 31366108, 2019). "Because NAF-1 is important for lifespan control and autophagy, NAF-1 is associated with proliferation and apoptosis in breast cancer." (PMID 29765509, 2018). "Suppression (shRNA) of mNT [mNT(-)] or NAF-1 [NAF-1(-)] expression in human epithelial breast cancer cells (MCF-7 or MDA-MB-231) resulted in the disruption of MMP, the over-accumulation of labile iron and ROS in mitochondria and the activation of autophagy." (PMID 28426722, 2017). "Here we show that small hairpin (sh)RNA-mediated suppression of NAF-1 results in the activation of apoptosis in epithelial breast cancer cells and xenograft tumors." (PMID 26621032, 2016). "Our studies suggest that NAF-1 is a major player in the metabolic regulation of breast cancer cells through its effects on cellular Fe ion distribution, mitochondrial metabolism and the induction of apoptosis." (PMID 26621032, 2016). "Metabolomics and transcriptomics analysis of breast cancer cells in which NAF-1 had been suppressed revealed a further shift towards glycolysis and glutaminolysis, and the activation of cellular stress pathways associated with HIF1α." (PMID 26621032, 2016). "To explore the potential of NAF-1 to affect Fe ion and ROS metabolism in cancer cells, we examined the level of expression of transferrin receptors and the site of ROS accumulation in breast cancer cells with suppressed NAF-1 expression." (PMID 26621032, 2016). "Here, we report that small hairpin (sh)RNA-mediated suppression of NAF-1 in human breast cancer cells results in the activation of apoptosis in xenograft MDA-MB-231 tumors and in MCF-7 or MDA-MB-231 cells grown in culture." (PMID 26621032, 2016). "Suppression of NAF-1 expression in human breast cancer cells appears, therefore, to reduce their tumorigenicity by interfering with cellular Fe ion distribution and energy metabolism, resulting in the enhanced accumulation of Fe ions and ROS in the mitochondria, and the activation of apoptosis." (PMID 26621032, 2016). "The findings that NAF-1(−) cells have an even higher dependency on glycolysis compared to control breast cancer cells suggest that anti-glycolytic cancer therapies might be successfully used in conjunction with therapies targeting NAF-1–BCL-2 interactions." (PMID 26621032, 2016). "MNT(-)/NAF-1(-) double suppressed human epithelial breast cancer cell lines did not display a significantly larger impairment in their MMP, or a higher over-accumulation of labile iron or ROS in their mitochondria compared to NAF-1(-) or mNT(-) single suppressed lines." (PMID 28426722, 2017). "This small molecule has recently been found to target breast cancer cells without any apparent effect on normal breast cells, a specificity that could reflect the high levels of NAF-1 and BCL-2 in these cells." (PMID 26621032, 2016). "We recently reported that a peptide derived from the human mitochondrial/ER membrane-anchored NEET protein, Nutrient Autophagy Factor 1 (NAF-1; NAF-144-67), selectively permeates and kills human metastatic epithelial breast cancer cells (MDA-MB-231), but not control epithelial cells." (PMID 37652915, 2023).
diabetes (7 papers, 2013 to 2024). "Both mNT and NAF-1 have been implicated in a number of human pathologies including diabetes, neurodegeneration, myocardial injury and cancer, as well as in development, differentiation and aging." (PMID 28426722, 2017). "NAF-1 and mNT are also implicated in a number of other human pathologies including diabetes, neurodegeneration and cardiovascular disease, as well as in development, differentiation and aging." (PMID 28426722, 2017). "While the genes encoding NAF-1 are WFS-1 and mutant CISD2, this gene is present in Wolfram syndrome type 2 (WFS-T2), so the pancreatic β-cells ferroptosis due to NAF-1 deficiency may be the mechanism of diabetes associated with WFS-T2." (PMID 38693581, 2024). "Other studies also found that MitoNEET and NAF-1 play a vital role in the pathology of obesity, diabetes, heart disease, neurodegeneration, and cancer progression." (PMID 34497268, 2021).
coronary artery disease (4 papers, 2016 to 2024). "The rs11125529, rs7675998, rs8105767, and rs7194734 SNPs belong to the ACYP2, NAF1, ZNF208, and MPHOSPH6 genes, respectively, which were found to be associated with increasing risk of developing coronary heart disease." (PMID 38293941, 2024). "Furthermore, genome-wide association studies of adult leukocyte TL (LTL) identified 7 single-nucleotide variations (ACYP2, NAF1, OBFC1, RTEL1, TERC, TERT, ZNF208) linked with LTL that mutually project towards an increased risk for coronary artery disease." (PMID 35930283, 2022).
Wolfram syndrome 2 (4 papers, 2017 to 2024). Any Wolfram syndrome in which the cause of the disease is a mutation in the CISD2 gene. "A NAF-1 dysfunctional variant was also found to be the causative agent of the human monogenic genetic disease Wolfram Syndrome 2 (WFS2) that is associated with juvenile diabetes, hearing deficiencies, neurodegeneration, blindness, and lower life expectancy." (PMID 29556009, 2018).
glioma (3 papers, 2015 to 2022). A benign or malignant brain and spinal cord tumor that arises from glial cells (astrocytes, oligodendrocytes, ependymal cells). "Through a series of systematic in vitro and in vivo studies, we demonstrate that NAF1 is a functional oncogene, and there may form positive feedback loops between NAF1 and numerous key molecules associated with malignant progression of gliomas via the regulation of ribosome biosynthesis." (PMID 30936423, 2019). "Collectively, NAF1 is crucial for ribosome biogenesis, and contributes to malignant phenotypes of glioma cells such as proliferation, survival, and metastasis." (PMID 30936423, 2019). "Next, we attempted to determine the effect of NAF1 on protein synthesis ability through observing the production of exogenous GFP proteins in glioma cells." (PMID 30936423, 2019). "Second, we discovered that NAF1 depletion in glioma cells significantly inhibited cell proliferation, colony formation, migration, invasion, and tumorigenic ability in nude mice, and induced cell apoptosis." (PMID 30936423, 2019). "We also attempted to assess the impact of NAF1 depletion on the migration and invasion abilities of glioma cells." (PMID 30936423, 2019). "Further studies reveal that NAF1 promotes glioma tumorigenesis and progression through enhancing ribosome biogenesis and protein synthesis." (PMID 30936423, 2019). "Next, we explored the connection between their expression and NAF1 expression in gliomas using TCGA dataset." (PMID 30936423, 2019). "Most importantly, by visualizing the distribution of AHA-labeled newly synthesized proteins, we demonstrated that NAF1 indeed enhanced protein synthesis through promoting the ability of ribosome biosynthesis in glioma cells." (PMID 30936423, 2019). "These molecules in turn enhanced the transcription and translation of NAF1, thereby forming positive feedback loops between them to promote malignant phenotypes of glioma cells." (PMID 30936423, 2019). "The results showed that NAF1 knockdown dramatically inhibited migration and invasion potential of glioma cells relative to control cells." (PMID 30936423, 2019). "However, in humans, the physiological function of NAF1 and its association with the crucial biological processes during carcinogenesis remain uncertain; thus we speculate that NAF1 promotes glioma tumorigenesis and progression through regulating the assembly and function of ribosomes." (PMID 30936423, 2019). "The results indicated that, relative to control subjects, the mRNA and protein levels of NAF1 were clearly upregulated in gliomas." (PMID 30936423, 2019). "In this study, we found that NAF1 was highly expressed in gliomas relative to normal brain tissues, and demonstrated that increased expression of NAF1 was strongly correlated with poor patient survival." (PMID 30936423, 2019). "Collectively, these results indicate that c-Myc, NRF2, and TERT can transcriptionally regulate NAF1 in glioma cells." (PMID 30936423, 2019). "In summary, we find that NAF1 is highly expressed in gliomas, and the increased expression of NAF1 is closely connected with poor patient survival." (PMID 30936423, 2019). "In this study, we first proved that NAF1 was significantly elevated in gliomas relative to normal brain tissues, and found the correlation of increased expression of NAF1 with poor prognosis in LGG patients." (PMID 30936423, 2019). "In conclusion, our data showed that NAF1 promotes glioma tumorigenesis and progression probably through enhancing ribosome assembly and protein synthesis." (PMID 30936423, 2019). "Conversely, ectopic expression of NAF1 obviously enhanced malignant phenotypes of glioma cells, indicating that NAF1 is a functional oncogene in gliomas." (PMID 30936423, 2019). "To clarify the mechanism underlying NAF1 upregulation in gliomas, we predicted and identified two important transcription factors c-Myc and NRF2 probably regulating NAF1 transcription." (PMID 30936423, 2019).
glioma (continued). "A series of loss- and gain-of-function experiments were performed in vitro to define the biological function of NAF1 in glioma." (PMID 30936423, 2019). "We first performed qRT-PCR, immunohistochemistry (IHC), and western blot assays to examine mRNA and protein levels of NAF1 in gliomas (n = 30) and normal brain tissues (n = 8; controls)." (PMID 30936423, 2019). "Therefore, we explored the correlation of NAF1 expression with clinicopathologic and genetic characteristics in gliomas using the TCGA dataset." (PMID 30936423, 2019). "Moreover, we demonstrated that NAF1 was a functional oncogene in glioma cells through promoting cell growth in vitro and in vivo, survival, migration, and invasion." (PMID 30936423, 2019). "During ribosome biogenesis, high expression of NAF1 enhances the assembly of 40S subunits and protein synthesis ability through increasing the levels of U17 snoRNA and accelerating 18S rRNA maturation in gliomas cells." (PMID 30936423, 2019). "Then, we investigated the impact of NAF1 depletion on glioma cell apoptosis." (PMID 30936423, 2019). "To determine whether aberrant expression of NAF1 in glioma cells can perturb the accumulation of ribosomal 40S subunits, we performed the sucrose gradient centrifugation." (PMID 30936423, 2019). "Further studies revealed that NAF1 was transcriptionally regulated by c-Myc, NRF2, and telomerase reverse transcriptase (TERT), which are the key molecules associated with malignant progression of gliomas." (PMID 30936423, 2019). "However, the specific biological role and exact mechanism of NAF1 in human cancers including glioma remain largely unclear." (PMID 30936423, 2019). "Our data showed that NAF1 expressions were decreased upon c-Myc or NRF2 knockdown in glioma cells, while the mRNA and protein levels of NAF1 were increased upon overexpression of c-Myc or NRF2, suggesting that NAF1 may be a potential target of c-Myc and NRF2." (PMID 30936423, 2019). "Altogether, these results indicated that NAF1 is a functional oncogene in glioma." (PMID 30936423, 2019). "Taken together, we demonstrated that NAF1 promotes the tumorigenesis and progression of glioma through modulating ribosome assembly and protein synthesis, and predicted that NAF1 may be a potential therapeutic target and valuable prognostic biomarker in gliomas." (PMID 30936423, 2019). "Moreover, by a series of in vitro and in vivo experiments, we demonstrate that NAF1 may be a potent oncogene in glioma cells." (PMID 30936423, 2019). "To address this, we first determined whether NAF1 expression was regulated by TERT in glioma cells." (PMID 30936423, 2019). "Thus, we speculate that NAF1 promotes glioma tumorigenesis and progression probably through enhancing ribosome biosynthesis." (PMID 30936423, 2019). "Thus, NAF1 may be used as a valuable prognostic marker and even a potential therapeutic target for gliomas." (PMID 30936423, 2019). "Thus we supposed that NAF1 may function on 18S pre-rRNA cleavage processing by affecting U17 expression, thereby modulating ribosomal biogenesis in glioma cells." (PMID 30936423, 2019). "Gliomas and CRC are two very different cancer types, and it is therefore possible that NAF1 functions differently in the two cancer types." (PMID 36067202, 2022). "Therefore, we hypothesize that NAF1 may participate in telomere length maintenance in glioma cells." (PMID 30936423, 2019). "Thus, there may be positive feedback loops between NAF1 and these key molecules in glioma cells." (PMID 30936423, 2019). "Altogether, our findings showed that NAF1 is transcriptionally regulated by c-Myc and NRF2 in glioma cells." (PMID 30936423, 2019). "Thus, we speculate that NAF1 depletion in glioma cells may result in nucleolar/ribosomal stress." (PMID 30936423, 2019). "Thus, we supposed that TERT may be involved in regulating NAF1 transcription in glioma cells." (PMID 30936423, 2019).
glioma (continued). "Next, we assessed the effect of NAF1 knockdown on glioma cell growth in vitro, and found that the proliferation of SF295 and U87 cells was significantly inhibited upon siRNA-mediated NAF1 knockdown compared to the controls." (PMID 30936423, 2019). "Altogether, our data suggest that NAF1 lengthens telomere length through regulating TERT at both transcription and translation levels and TERC at transcription levels in glioma cells." (PMID 30936423, 2019). "Thus, we suppose that aberrant expression of NAF1 will impact the translation of key molecules in malignant progression of gliomas such as c-Myc, NRF2, and TERT, which have been demonstrated to regulated NAF1 transcription." (PMID 30936423, 2019). "Mechanistically, NAF1 maintains telomere length through regulating two major components of telomerase, TERT and TERC37, at transcription and/or translation levels, thereby contributing to malignant progression of gliomas." (PMID 30936423, 2019). "However, we surprisingly found that knockdown or ectopic expression of NAF1 in glioma cells also impacted mRNA levels of c-Myc, NRF2, and TERT, suggesting that there may exist unknown mechanisms of NAF1 modulating gene transcription." (PMID 30936423, 2019).
colon cancer (2 papers, 2019 to 2022). "The possible gene regulatory region with the risk allele SNP rs17042479(G) reduced the NAF1 promoter activity by 18%, 38% and 34% in the three colon cancer cell lines Caco2, DLD-1 and SW480, respectively." (PMID 36067202, 2022). "The possible gene regulatory region with the reference allele SNP rs17042479 (A) significantly reduced the promoter activity of NAF1 by 18% and 11% in the two colon cancer cell lines DLD-1 and SW480, respectively." (PMID 36067202, 2022). "Analyzing the NAF1 promoter activity in different constructs yielded similar results in the three colon cancer cell lines: Caco2, DLD-1, and SW480." (PMID 36067202, 2022). "The NAF1 promoter was highly active in the three colon cancer cell lines: SW480, DLD-1 and Caco2." (PMID 36067202, 2022). "Additionally, the NAF1 promoter, NAF1pro, was highly active in all three colon cancer cell lines Caco2, DLD-1 and SW480." (PMID 36067202, 2022). "We analyzed the promoter activity of NAF1 and FSTL5 in the three colon cancer cell lines Caco2, DLD-1 and SW480 in a promoter reporter gene assay." (PMID 36067202, 2022). "The promoter activity analysis revealed that the FSTL5 promoter was not nearly as active in the three colon cancer cell lines as the NAF1 promoter." (PMID 36067202, 2022).
emphysema (2 papers, 2022). "Rare variants in NAF1 were shown to cosegregate with decreased expression of NAF-1, low TERC levels, short telomere length and a phenotype of familial pulmonary fibrosis and emphysema." (PMID 36221106, 2022).
Friedreich ataxia (2 papers, 2016 to 2021). An inherited condition that affects the nervous system and causes movement problems. "Taken together, the alterations in Fe ions and ROS in cancer cells with suppressed NAF-1 expression appear to resemble the alterations in Fe ions and ROS that are induced by the disruption of Fe-S biogenesis in conditions such as Friedreich's ataxia and in some forms of sideroblastic anemia." (PMID 26621032, 2016).
melanoma (2 papers, 2016 to 2023). A malignant, usually aggressive tumor composed of atypical, neoplastic melanocytes. "Some telomere length maintenance genes (TERC, OBFC1) regulate both nevus count and melanoma risk, while the majority regulate melanoma risk only (such as TERT, DKK2, NAF1)." (PMID 36834954, 2023).
Obesity (2 papers, 2021 to 2024). Accumulation of substantial excess body fat. "As dEF3122 targets NAF-1 and is largely distributed in the liver, it appears as an ideal candidate to be tested in a diet-induced obesity model of NASH." (PMID 38252831, 2024).
cervical cancer (1 paper, 2020). A primary or metastatic malignant neoplasm involving the cervix. "In recent years, NAF-1 has gained increasing interest, and it was found that NAF-1 expression is increased in a variety of tumors, including gastric cancer, prostate cancer, cervical cancer, liver cancer, and laryngeal cancer." (PMID 32766132, 2020).
colorectal cancer (1 paper, 2022). A primary or metastatic malignant neoplasm that affects the colon or rectum. "A novel risk locus at 4q32.2, located between the Nuclear Assembly Factor 1 (NAF1) and Follistatin Like 5 (FSTL5) genes, was associated with increased risk of developing colorectal cancer (CRC), with SNP rs17042479 being the most associated." (PMID 36067202, 2022).